WNT2B (Wnt family member 2B)
Diseases named in the same sentence as WNT2B in open-access papers (continued):
Sharing a sentence is not in itself a finding about the gene and the disease.
cancer (continued). "In addition, the horizontal transfer of exosomal Wnt2B secreted by CC cells into fibroblasts may promote the transition of NFs into CAFs by activating the Wnt/β-catenin pathway, which is capable of stroma remodeling and cancer progression." (PMID 33731705, 2021). "FZD8, plasminogen activator, urokinase receptor, ITGA2, WNT2B, TIMP3, WNT5B, FGF5, heparanase, HBEGF and WNT3A were up-regulated in the proteoglycan pathways in cancer, whereas WNT10A, PIK3R3, IGF2 were down-regulated." (PMID 30482199, 2018). "Our results demonstrated that 5 of the 6 up-regulated mRNAs in “HTLV-1 infection pathway” increased (ICAM1, WNT2B, MYC, HLA-F and TGF-β1) and 3 of the 5 down-regulated mRNAs in “Pathways in cancers” decreased (CDH1, PTENP1, HSP90AA1)." (PMID 24367666, 2013). "To further verify whether circ_0088233 as a ceRNA of miR-185-3p, we investigated its effect on the level of circ_0088233 knockdown on the levels of WNT2B and E2F1, which are the targets of miR-185-3p identified in cancer cells." (PMID 33195183, 2020). "Fifteen members of cancer pathways, including FOS, TGFα, FZD8, MMP1, laminin subunit gamma 2, PTGS2, laminin subunit beta 3, ITGA2, laminin subunit alpha 3, VEGFC, WNT2B, heat shock protein 90 beta family member 1, WNT5B, FGF5 and WNT3A, were up-regulated in the MC group." (PMID 30482199, 2018). "A second member of the WNT family, WNT2B, is expressed in CS1 but not CS2 suggesting, contrary to what is presented above, that CS1 may be more permissive for cancer growth." (PMID 23762861, 2013).
infection (2 papers, 2013). The state of being infected such as from the introduction of a foreign agent such as serum, vaccine, antigenic substance or organism. "Semi-quantitative PCR revealed significant increases in both Wnt2b and Wnt5a expression in YAMC cells at 48 h post-CR infection compared to uninfected control." (PMID 24278135, 2013). "In response to siRNA-mediated Wnt2b knockdown, reporter activity decreased significantly and was not rescued with CR infection." (PMID 24278135, 2013). "Our data revealed a secretion of WNT2B that build-up until 8 hours post-infection, while no secretion was observed with IFN-α treatment." (PMID 23785285, 2013). "Interestingly, purified Wnt2b was more potent than even CR infection in facilitating β-catenin’s nuclear import while a combination of Wnt2b+CR did not necessarily yield an additive response." (PMID 24278135, 2013). "Thus, Wnt5a and not Wnt2b regulates NF-κB activity in response to CR infection." (PMID 24278135, 2013).
adenocarcinoma (1 paper, 2016). A common cancer characterized by the presence of malignant glandular cells. "In such adenocarcinomas frequent up-regulation of Wnt2B is found." (PMID 27438855, 2016).
intestinal disease (1 paper, 2023). "The significance of WNT2B in intestinal biology was relatively poorly understood until the finding of human WNT2B mutations linked to intestinal disease." (PMID 36422736, 2023). "Three out of the four reported patients were also found to have significant anterior chamber abnormalities (microcornea, colobomas) establishing WNT2B disease as an occulo-intestinal disorder." (PMID 36422736, 2023).
neurodegenerative disease (1 paper, 2023). A disorder of the central nervous system characterized by gradual and progressive loss of neural tissue and neurologic function. "And we consider AD is a very complex neurodegenerative disease, and the cognitive diagnosis and assessment of AD should be comprehensive, rather than Wnt2b." (PMID 36852442, 2023).
neurological diseases (1 paper, 2023). "Our results provide some reference for Wnt2b in diagnosing neurological diseases including AD." (PMID 36852442, 2023).
WNT2B also shares sentences with these, for which no sentence is quoted: colorectal cancer (4 papers); leukemia (2); lung adenocarcinoma (2); anaplastic large cell lymphoma (1); atherosclerosis (1); autism spectrum disorder (1); basal cell carcinoma (1); depression (1); diabetes (1); diabetic nephropathy (1); enteropathy (1); esophageal cancer (1); glioma (1); Huntington disease (1); Hyperinsulinemia (1); hyperlipidemia (1); hypopharyngeal squamous cell carcinoma (1); mesothelioma (1); osteoarthritis (1); osteosarcoma (1); papillary thyroid carcinoma (1); Parkinson disease (1); polyp (1); primary biliary cirrhosis (1); skin cutaneous melanoma (1); squamous cell lung carcinoma (1); thymoma (1); thyroid cancer (1); triple-negative breast carcinoma (1); type II diabetes (1).
A further 2 diseases each share a sentence with WNT2B in 1 paper.